EP400 (E1A binding protein p400)
Description:
Component of the NuA4 histone acetyltransferase complex which is involved in transcriptional activation of select genes principally by acetylation of nucleosomal histones H4 and H2A. This modification may both alter nucleosome - DNA interactions and promote interaction of the modified histones with other proteins which positively regulate transcription. May be required for transcriptional activation of E2F1 and MYC target genes during cellular proliferation. The NuA4 complex ATPase and helicase activities seem to be, at least in part, contributed by the association of RUVBL1 and RUVBL2 with EP400. May regulate ZNF42 transcription activity. Component of a SWR1-like complex that specifically mediates the removal of histone H2A.Z/H2AZ1 from the nucleosome.
Synonyms: CAGH32; KIAA1498; KIAA1818; TNRC12; P400; DKFZP434I225
Tractability: Small molecule: a structure with a bound ligand is known. PROTAC: ubiquitination databases record sites on it; its protein half-life has been measured.
Gene: Protein-coding gene on chromosome 12 (131,949,931 to 132,080,460, forward strand). Ensembl gene ENSG00000183495.
Subcellular location: Nucleus
Subcellular location (Human Protein Atlas): Nucleoplasm
Pathways (Reactome):
Cellular responses to stimuli: DNA Damage/Telomere Stress Induced Senescence; Formation of Senescence-Associated Heterochromatin Foci (SAHF)
Chromatin organization: HATs acetylate histones
Gene Ontology:
Molecular function: protein binding; chromatin binding; ATP binding; protein antigen binding
Biological process: nervous system development; positive regulation of double-strand break repair via homologous recombination; regulation of cell cycle; DNA repair; positive regulation of DNA-templated transcription; regulation of apoptotic process; regulation of double-strand break repair
Cellular component: NuA4 histone acetyltransferase complex; nucleoplasm; nucleosome; Swr1 complex; nuclear speck; nucleus
Genetic constraint (gnomAD): Loss-of-function variants: 105 observed, 338.29 expected, observed/expected ratio (o/e) 0.31, 90% interval 0.26 to 0.37. The upper end of that interval is the gene's LOEUF score, 0.37, which puts it in group 1 of 6, group 1 being the genes least tolerant of losing a copy. Missense variants: 3,246 observed, 3,963.6 expected, observed/expected ratio (o/e) 0.82, 90% interval 0.8 to 0.84. Synonymous variants: 1,632 observed, 1,643.9 expected, observed/expected ratio (o/e) 0.99, 90% interval 0.95 to 1.03.
Homologues: Orthologues: chimpanzee EP400 (99% identical), macaque EP400 (95% identical), rat Ep400 (86% identical), guinea pig EP400 (85% identical), rabbit EP400 (84% identical), mouse Ep400 (84% identical), pig EP400 (82% identical), dog EP400 (77% identical), tropical clawed frog ep400 (57% identical), zebrafish ep400 (51% identical). Paralogues in human: SRCAP (23% identical), CHD7 (12% identical), SMARCA4 (11% identical), CHD9 (11% identical), SMARCA2 (11% identical), CHD2 (11% identical), CHD5 (11% identical), INO80 (10% identical), CHD1 (10% identical), CHD4 (10% identical), CHD3 (10% identical), CHD8 (10% identical), and 18 more.
Diseases named in the same sentence as EP400 in open-access papers:
EP400 is named in the same sentence as 36 diseases in open-access papers, as found by Europe PMC text mining. Sharing a sentence is not in itself a finding about the gene and the disease. The quoted sentences say what the papers report.
schizophrenia (2 papers, 2021). A major psychotic disorder characterized by abnormalities in the perception or expression of reality. "A missense variant, chr12:132064747C>T (rs200626129, P2805L), in the E1A-binding protein P400 (EP400) gene completely segregated with schizophrenia in this family." (PMID 33602898, 2021). "In conclusion, we identified a unique missense variant in EP400 through the exome sequencing of a Japanese family containing multiple schizophrenia patients." (PMID 33602898, 2021). "Using WES, the present study identified a unique missense variant in the E1A-binding protein P400 (EP400) gene in a Japanese family in which several members were affected by severe schizophrenia/TRS." (PMID 33602898, 2021). "Furthermore, numerous other EP400 mutations were identified in the targeted sequencing of a schizophrenia patient cohort." (PMID 33602898, 2021). "The phenotypes of the Ep400 gene-edited mice may not be generalisable, because the burden of rare variants in EP400 on the development of schizophrenia remains unclear." (PMID 33602898, 2021). "However, the phenotypes observed in Ep400 gene-edited mice in the present study are not likely to be easily generalisable, especially considering that the burden of rare variants in EP400 on the development of schizophrenia remains unclear." (PMID 33602898, 2021).
Anxiety (1 paper, 2021). Intense feelings of nervousness, tension, or panic often arise in response to interpersonal stresses. "Ep400-p.P2715L mice, corresponding to the human P2805L mutation, showed anxiety-like behaviour and had decreased axon diameters in the spinal cord white matter." (PMID 33602898, 2021). "We also created two lines of Ep400 gene-edited mice, which had anxiety-like behaviours and reduced axon diameters." (PMID 33602898, 2021).
bladder cancer (1 paper, 2016). "Taken together, the mutations of MLL, EP400 and PRDM2 may be involved in bladder carcinoma relapse." (PMID 26625313, 2016). "After discovery and confirmation, five genes MLL, EP400, PRDM2, ANK3 and CHD5 significantly correlated with the recurrence of bladder cancer." (PMID 26625313, 2016). "Additionally, the contribution of specific alterations of EP400, PRDM2, ANK3 and CHD5 to bladder carcinoma recurrence should also be further investigated." (PMID 26625313, 2016).
Chordoid Meningioma (1 paper, 2022). A WHO grade II, usually recurring meningioma characterized by the predominance of tissues that are histologically similar to chordoma. "Chordoid meningiomas were enriched in mutations in chromatin remodeling genes EP400 (8/11,73%) KMT2C (4/11, 36%) and KMT2D (4/11, 36%), and showed low or absent NF2, TERT, SMO, and AKT1 mutations." (PMID 35440040, 2022). "Our chordoid cohort was relatively enriched in chromatin remodeling genes EP400, KMT2C and KMT2D mutations compared to non-chordoid meningiomas." (PMID 35440040, 2022).
colorectal cancer (1 paper, 2017). A primary or metastatic malignant neoplasm that affects the colon or rectum. "The E1A binding protein p400 (EP400, 12q24.33) was reported to be associated with cancers such as RCC and colorectal cancer." (PMID 28249600, 2017).
endometrial stromal sarcoma (1 paper, 2021). "Intriguingly, besides AML-related ZM fusion, aberrant chromosomal rearrangements detected in endometrial stromal sarcoma patients recurrently target components of NuA4/TIP60 complex such as EP400, EPC1, EPC2, MEAF6 and MBTD146–50." (PMID 33594072, 2021).
hepatocellular carcinoma (1 paper, 2015). A malignant tumor that arises from hepatocytes. "Shi M et alfound a three-gene expression signature associated to early human hepatocellular carcinoma, constituted by the chemokine (C-X-C motif) receptor 2 (CXCR2), C–C chemokine receptor type 2 (CCR2) and the E1A-Binding Protein P400 (EP400)." (PMID 26317806, 2015).
melanoma (1 paper, 2024). A malignant, usually aggressive tumor composed of atypical, neoplastic melanocytes. "EP400, Mi-2β, PRDM4, NCOA6 or CARM1 silencing significantly induced the response to T-cell attack in melanoma cells, and led to more than 20% of the melanoma cells to be eliminated by T-cell-mediated killing." (PMID 38461299, 2024).
nevus (1 paper, 2021). Nevus (or naevus, plural nevi or naevi, from nævus, Latin for "birthmark") is the medical term for sharply circumscribed[1] and chronic lesions of the skin or mucosa. "NIPBL, AKAP9, and EP400 were mutated in both the nevus and atypical tumor, although the specific mutations were different between the two lesions." (PMID 35052351, 2021).
cancer (19 papers, 2010 to 2024). A tumor composed of atypical neoplastic, often pleomorphic cells that invade other tissues. "Mutations in EP400, a chromatin‐remodeling protein and a transcriptional repressor, may activate gene expression implicated in FL oncogenesis, as is the case with other cancers." (PMID 34791836, 2022). "Of clear relevance for potential therapeutic strategies, a recent report showed that loss of EP400 is synthetic lethal with perturbation of the SWI/SNF remodeler in cancer cell lines, a link supported by CRISPR screens and cancer patient data." (PMID 39088653, 2024). "Our results that five epidriver candidates (SRCAP, EP400, ARID1B, MBD5, and KMT2A) among the top 15 ERGs enriched in EMT fraction were found among the most mutated ERGs in clinical samples across cancer types support the driver role of EMT-specific ERG tumorigenesis." (PMID 32963031, 2020). "We identified 15 recurrent fusion gene pairs among all cancer types, with CHD7‐TOX (n = 4), EP400‐SFSWAP (n = 4), and SMARCA4‐DNM2 (n = 4) having the highest frequencies." (PMID 35789070, 2022). "Eventually, seven ATPCR encoding genes, including ATRX, CHD5, CHD7, SMARCA4, SMARCA2, EP400, and ACTB, were identified as driver genes by at least two algorithms in certain cancer types." (PMID 35789070, 2022). "Among the top most significant EMT-specific hits, one-third belonged to the category of histone methylation writers, whereas several ERGs (including KMT2A, EP400, MBD5, and SRCAP) were found to be frequently targeted by genetic alterations in several cancer types." (PMID 32963031, 2020). "The expression levels of EP400, HMGB2, CDK1, PPARG, and MVK were found to be significantly correlated with HMGA1 expression level in both analyzed cancer subtypes but not in non-cancerous tissue of the lung." (PMID 35805937, 2022). "We also found that six genes (TBP, EP400, DSPP, MUC21, MLLT3, and MUC2) were under negative selection in more than five cancer types." (PMID 28938601, 2017).
tumor (11 papers, 2010 to 2025). "Theoretically, ST could also function as a tumor initiator through its association with MYCL and the chromatin remodeling complex EP400, which leads to increased transcription of several pro-oncogenic genes." (PMID 33435392, 2021). "In addition, T3 had 120 mutations not found in the other tumours, including, for example, variants in ILF2 and IL7R, which regulate immune function, and in EP400 and POU2F1, which contribute to DNA repair mechanisms." (PMID 34299215, 2021).
neurological diseases (1 paper, 2024). "Recent studies have implicated GLS, RAI1, GIPC1, MED15, EP400, MEF2A, and CNKSR2 in neurological diseases, with GLS, GIPC1, MED15, RAI1, and MEF2A sharing the same repeat loci reported in this study." (PMID 38871700, 2024).
peripheral neuropathy (1 paper, 2019). A disorder affecting the peripheral nervous system. "Ep400 absence causes peripheral neuropathy in mice, characterized by terminal differentiation defects in myelinating and non-myelinating Schwann cells and immune cell activation." (PMID 31142747, 2019). "In the current study, the authors show that loss of Ep400 in Schwann cells leads to aberrant expression of developmental regulators, and a peripheral neuropathy phenotype." (PMID 31142747, 2019). "Mice with a Dhh::Cre-dependent deletion of both Tfap2a and Ep400, in contrast, exhibited an unsteady gait and impaired motor coordination as symptoms of a peripheral neuropathy." (PMID 31142747, 2019).
EP400 also shares sentences with these, for which no sentence is quoted: colon carcinoma (3 papers); breast carcinoma (2); epilepsy (2); lung adenocarcinoma (2); osteosarcoma (2); prostate carcinoma (2); renal cell carcinoma (2); viral infection (2); adenovirus infections (1); asthma (1); Ataxia (1); autism (1); conotruncal heart defects (1); cyst (1); glioma (1); infection (1); lung carcinoma (1); lung squamous cell carcinoma (1); Merkel cell carcinoma (1); metastatic disease (1); neuroblastoma (1); neurodevelopmental disorder (1); teratoma (1).